PLP2 (proteolipid protein 2)
Description:
May play a role in cell differentiation in the intestinal epithelium.
Synonyms: A4; A4-LSB; MGC126187; A4LSB
Tractability: Antibody: its Gene Ontology location is reachable by antibodies, with high confidence; UniProt predicts a signal peptide or a membrane-spanning region.
Gene: Protein-coding gene on chromosome X (49,171,787 to 49,175,235, forward strand). Ensembl gene ENSG00000102007.
Subcellular location: Membrane
Gene Ontology:
Molecular function: chemokine binding; protein binding; monoatomic ion transmembrane transporter activity
Biological process: chemotaxis; cytokine-mediated signaling pathway; monoatomic ion transport; monoatomic ion transmembrane transport
Cellular component: plasma membrane; endoplasmic reticulum; endoplasmic reticulum membrane; membrane
Homologues: Orthologues: macaque PLP2 (99% identical), chimpanzee PLP2 (97% identical), guinea pig PLP2 (85% identical), pig PLP2 (84% identical), rat Plp2 (82% identical), mouse Plp2 (80% identical), mouse Plp2rt (80% identical), rat Plp2l1 (76% identical), dog PLP2 (66% identical), zebrafish plp2b (44% identical), tropical clawed frog plp2 (42% identical), zebrafish plp2a (30% identical), and 2 more. Paralogues in human: CMTM3 (30% identical), CMTM5 (28% identical), CMTM1 (23% identical), CMTM2 (21% identical), MAL (21% identical), CMTM4 (20% identical), MARVELD1 (20% identical), CMTM8 (20% identical), CKLF (19% identical), CMTM6 (19% identical), PLLP (19% identical), CMTM7 (18% identical), and 2 more.
Diseases named in the same sentence as PLP2 in open-access papers:
PLP2 is named in the same sentence as 36 diseases in open-access papers, as found by Europe PMC text mining. Sharing a sentence is not in itself a finding about the gene and the disease. The quoted sentences say what the papers report.
melanoma (9 papers, 2013 to 2022). A malignant, usually aggressive tumor composed of atypical, neoplastic melanocytes. "The upregulation of PLP2 in melanoma, caused by miR-664 downregulation, enhances the proliferation and metastasis of melanoma via the PI3K/AKT pathway." (PMID 31803141, 2019). "Recently, PLP2 expression has been reported to be associated with tumor cell persistence and metastasis in melanoma and hematologic malignancies." (PMID 30373180, 2018). "PLP2 binds the ER-resident protein Bap31 and the chemokine receptor CCR1, and decreased PLP2 expression has been implicated in X-linked mental retardation and melanoma metastasis." (PMID 24278019, 2013). "The present work provides evidence that Rb4, derived from PLP2, triggers necrotic cell death in murine melanoma cells, in a dose-dependent manner, through ER stress caused by inhibition of SERCA transporter activity, which leads to alteration of actin dynamics and RIP1 inhibition." (PMID 35190586, 2022). "PLP2, a four-transmembrane domain protein, has contributed to the tumor formation and metastasis of murine melanoma in a syngeneic B16F10 model." (PMID 35190586, 2022). "Overexpression of Proteolipid protein 2 (PLP2) increased tumor metastasis and the knockdown of PLP2 inhibited the growth and metastasis of melanoma cells." (PMID 35190586, 2022). "PLP2 is significantly up-regulated in a variety of tumors, including breast cancer, hepatocellular carcinoma, osteosarcoma, and melanoma." (PMID 31850259, 2019). "Otherwise, PLP2 had been viewed as an oncogenic-inducer in several human cancers including melanoma, osteosarcoma, breast cancer, hepatocellular carcinomas, and acute lymphoblastic leukemia." (PMID 30373180, 2018). "On the other side, the expression of PLP2 on A2058 human melanoma cells could be down-regulated, decreasing the sensitivity of these cells to Rb4." (PMID 35190586, 2022). "In addition, the downregulation of PLP2 by microRNA-664 obviously inhibited melanoma and leukemic cell invasion and proliferation." (PMID 32596309, 2020). "In the recent study, PLP2 could stimulate matrix metalloprotease 2 (MMP2) secretions to induce melanoma cell proliferation, invasion and even metastasis." (PMID 30373180, 2018). "Additionally, the down-regulation of PLP2 expression by microRNA-664 significantly inhibited leukemic and melanoma cell proliferation and invasion." (PMID 30373180, 2018). "PLP2, a four-transmembrane domain protein located in the endoplasmic reticulum 19, 20, has been regarded as an oncogenic-inducer in several cancers including melanoma, osteosarcoma, breast cancer, hepatocellular carcinomas, and acute lymphoblastic leukemia 20-22." (PMID 33859750, 2021). "In this study, we investigated the cytotoxicity of Rb4, the N-terminal PLP2 peptide, against B16F10 murine melanoma in a syngeneic model." (PMID 35190586, 2022). "PLP2, a four-transmembrane domain protein, has an important role in tumor formation and metastasis of murine B16F10 melanoma in a syngeneic model." (PMID 35190586, 2022).
breast carcinoma (6 papers, 2012 to 2021). "PLP2 has been reported to be a target gene of miR-422a and is associated with regulating breast cancer." (PMID 34555810, 2021). "PLP2 has been demonstrated to be elevated in multiple cancers, such as hepatocellular carcinoma, breast cancer, and osteosarcoma." (PMID 34555810, 2021). "In breast cancer, PLP2 is the direct target of the tumor suppressor MiR-422a." (PMID 31803141, 2019). "There was no significant downregulation of PLP2 and XCL2 in MCF-7 breast cancer cells." (PMID 22134506, 2012).
glioma (6 papers, 2018 to 2025). A benign or malignant brain and spinal cord tumor that arises from glial cells (astrocytes, oligodendrocytes, ependymal cells). "However, more studies on the molecular mechanisms underlying PLP2 activity in glioma are warranted before translation of the strategy into clinical practice." (PMID 31778016, 2020). "Finally, intracranial xenografts derived from U87‐ and U251‐shPLP2 cells revealed that loss of PLP2 reduced glioma growth in vivo." (PMID 31778016, 2020). "Furthermore, of all included factors, senior glioma patient, PLP2 overexpression, loss of ATRX, and positive expression of AxL, NUR77 or PDGFRA were the independent prognostic factors under cox regression analysis." (PMID 30373180, 2018). "ZFAS1 induces glioma progression by sponging miR‐150‐5p to regulate proteolipid protein 2 (PLP2), which is known as the functional target of miR‐150‐5p." (PMID 33980320, 2021). "In functional experiments, siRNA and shRNA PLP2 knockdown induced ER stress and increased apoptosis and autophagy in U87 and U251 glioma cell lines." (PMID 31778016, 2020). "Taken together, our results demonstrate that inhibition of autophagy augments apoptotic cell death induced by PLP2 knockdown in U87 and U251 glioma cell lines." (PMID 31778016, 2020). "In conclusion, down‐regulation of PLP2 also induces autophagy which is mediated in part by ER stress‐induced CHOP in glioma cells." (PMID 31778016, 2020). "Using publicly available datasets (Rembrandt, TCGA and CGGA), we found that the expression of PLP2 was significantly higher in high‐grade gliomas than in low‐grade gliomas." (PMID 31778016, 2020). "We investigated the significance of this finding through PLP2 knockdown in U87 and U251 glioma cell lines in vitro and in vivo." (PMID 31778016, 2020). "We first examined the levels of PLP2 expression in human glioma samples by analysing publicly available datasets from Rembrandt, The Cancer Genome Atlas (TCGA) and the Chinese Glioma Genome Atlas (CGGA)." (PMID 31778016, 2020). "Our work therefore identifies PLP2 as a potential oncogene in glioma progression and provides a putative rationale for using the protein as a prognostic marker, or as a target in treatment of the disease." (PMID 31778016, 2020). "Since soft agar colony formation test is an ideal tool for quantitative assessing cancer cell proliferation and migration, we performed this assay to evaluate the ability for tumor tumorigenicity in gliomas with a PLP2 knockdown." (PMID 30373180, 2018). "To evaluate PLP2 mRNA expression in human glioma cell lines, we applied quantitative RT-PCR on cDNA isolated from normal brain tissue and four different clones of glioma cell lines including GBM8401, LN229, U87MG, and U118MG." (PMID 30373180, 2018). "To evaluate PLP2 expression in human glioma tissues, we performed IHC staining for PLP2 on 2 tissue microarray slides of various World Health Organization (WHO) grades of gliomas." (PMID 30373180, 2018). "In conclusion, we successfully demonstrated that PLP2 overexpression played an oncogenic role in glioma development and aggressive tumor behavior." (PMID 30373180, 2018). "On the contrary, higher PLP2 expression significantly correlated with more advanced tumor grades of gliomas (p = 0.039)." (PMID 30373180, 2018). "Since GBM8401 and LN229 glioma cell lines revealed higher PLP2 mRNA expression than U87MG, and U118MG, GBM8401 and LN229 glioma cell were transfected with siPLP2 and siRNA-A (scramble siRNA) (NC)." (PMID 30373180, 2018). "Otherwise, in order to evaluate PLP2 with other glioma-related genes expression, we performed univariate or multivariate analysis to detect the possible PLP2 associated risk factors." (PMID 30373180, 2018). "This study successfully proves that PLP2 induces tumor overgrowth and correlates with poor prognosis in glioma patients." (PMID 30373180, 2018).
glioma (continued). "After then, the alteration of PLP2 suppressed glioma cells behavior were examined by cell proliferation, wound healing, cell invasion, and colonies formation assays." (PMID 30373180, 2018). "First, we performed western-blot analysis, real-time quantitative PCR and immunohistochemical stains to detect PLP2 expression in 4 glioma cell lines and human glioma tissues." (PMID 30373180, 2018). "In this study, we performed in vitro studies, tissue microarrays, and immunohistochemical stains to detect the possible role of PLP2 in glioma." (PMID 30373180, 2018). "The cut-off of PLP2 immunostain scores was set at 40 for gliomas based on the relatively equal number of cases in each group." (PMID 30373180, 2018). "Compared with normal brain cell lysates and mRNA, all glioma cell lines displayed PLP2 protein and mRNA overexpression." (PMID 30373180, 2018). "We further show that down‐regulation of PLP2 inhibits the proliferation of glioma cells in vitro." (PMID 31778016, 2020). "Taken together, these results indicate that PLP2 has an important role in glioma progression." (PMID 31778016, 2020). "Therefore, we successfully demonstrated that PLP2 is an important cell proliferative factor in glioma cells, especially the LN229 glioma cell line." (PMID 30373180, 2018). "Therefore, in an in vitro study, we demonstrated the phenomenon of PLP2 overexpression in all human glioma cell lines." (PMID 30373180, 2018). "Additionally, to detect the overall survival time with PLP2 expression, we divided all gliomas into two groups based on high and low PLP2 expression." (PMID 30373180, 2018). "PLP2 could prevent normal neuronal cell apoptosis and oxidative stress apoptosis, but unfortunately, PLP2 increases glioma aggressive behavior." (PMID 30373180, 2018). "Although the precise mechanism of PLP2 in gliomas remains unclear, PLP2 might be a potential target to prolong overall survival, delay disease progression, and suppress tumor infiltration." (PMID 30373180, 2018). "Besides, higher PLP2 IHC staining significantly correlated with more advanced tumor grades and poorer prognosis in human gliomas." (PMID 30373180, 2018). "Additionally, we also performed western-blot analysis to evaluate the association between PLP2 and cell-cycle checkpoints in the LN229 and GBM8401 glioma cells." (PMID 30373180, 2018). "Furthermore, the consistent results from in vitro studies and human tissue specimens supplied strong evidence to prove the oncogenic role of PLP2 in glioma." (PMID 30373180, 2018). "Similarly, we demonstrated the relationship between PLP2 expression and glioma cell proliferation, migration, invasion, and metastatic characters." (PMID 30373180, 2018). "All glioma cell lines presented higher PLP2 mRNA expression than normal brain tissue cDNA." (PMID 30373180, 2018). "In addition, our tissue microarray study showed that PLP2 IHC staining is positively correlated with tumor grade and poor survival time in human gliomas." (PMID 30373180, 2018). "Similarly, less trans-membranous siPLP2 transfected LN229 glioma cells indicated that the suppression of PLP2 could inhibit tumor invasive behavior (p < 0.01)." (PMID 30373180, 2018). "Therefore, the inhibition of PLP2 expression could effectively decrease glioma cell spheres formation." (PMID 30373180, 2018). "Collectively, these data show that down‐regulation of PLP2 expression induces ER stress and promotes apoptosis which is partially dependent on CHOP in glioma cells." (PMID 31778016, 2020). "Additionally, PLP2 suppression may inhibit glioma cell migration and invasion." (PMID 30373180, 2018). "Proteolipid protein 2 (PLP2), a membrane protein of the endoplasmic reticulum, is related to tumor proliferation and metastasis in some human cancers, but not in gliomas." (PMID 30373180, 2018).
glioma (continued). "In this study, we showed that PLP2 IHC staining can not only discriminate glioma from non-neoplastic brain tissue, but also help clinical doctors and pathologists predict tumor aggressiveness and overall prognosis." (PMID 30373180, 2018). "In addition, we used small interfering RNA (SiPLP2) and short hairpin RNA (shPLP2) to knockdown PLP2 expression in GBM8401 and LN229 glioma cell lines." (PMID 30373180, 2018). "Although the detailed mechanism remained undetermined, our results supported PLP2 could induce cell cycle checkpoint dysregulation, stimulate extracellular matrix factors overexpression and enhance Raf/MEK/ERK signaling pathway in glioma tumorigenesis." (PMID 30373180, 2018). "Therefore, we discovered that PLP2 expression could up-regulate the p-p38 and p-ERK pathways and induced glioma cell proliferation, migration, and invasion." (PMID 30373180, 2018).
hepatocellular carcinoma (6 papers, 2013 to 2022). A malignant tumor that arises from hepatocytes. "In hepatocellular carcinoma, an amplitude-modulated electromagnetic field was reported to inhibit the proliferation of cancer cells via PLP2 downregulation." (PMID 31803141, 2019). "To demonstrate that PLP2 was required for K5 function in a cell type other than KBM7, we found that K5 was unable to decrease cell surface MHC-I expression in hepatocellular carcinoma HepG2 cells, which do not express PLP2." (PMID 24278019, 2013).
osteosarcoma (4 papers, 2019 to 2021). A usually aggressive malignant bone-forming mesenchymal neoplasm, predominantly affecting adolescents and young adults. "miR-664-3p may be involved in the occurrence and development of osteosarcoma, and can regulate the proliferation and apoptosis of U2-OS cells, and the expression of PLP2." (PMID 31850259, 2019).
cervical cancer (2 papers, 2022 to 2024). A primary or metastatic malignant neoplasm involving the cervix. "Through our analysis, we have discerned C3 PLP2+ Tumor Epithelial Progenitor Cells as a noteworthy subpopulation in cervical carcinoma (CC), exerting a pivotal influence on the differentiation and progression of CC." (PMID 38482016, 2024). "In summary, our investigation elucidated alterations in the tumor microenvironment and highlighted the pivotal role of the C3 PLP2+ Tumor Epithelial Progenitor Cells subpopulation in the onset and progression of cervical carcinoma (CC)." (PMID 38482016, 2024).
endometrial cancer (2 papers, 2021 to 2022). Primary or metastatic malignant neoplasm involving the endometrium (mucous membrane that lines the endometrial cavity). "In addition, the circulating miR-765 was shown to promote endometrial cancer development via the ERβ/miR-765/PLP2/Notch axis." (PMID 35740327, 2022).
alopecia (1 paper, 2024). Hair loss usually from the scalp. "In addition, the goat PLP2 (proteolipid protein 2) gene expressed only in the inner root sheath, suggesting that it may be associated with alopecia." (PMID 38628581, 2024).
clear cell renal cell carcinoma (1 paper, 2021). "By downregulating proteolipid protein 2 (PLP2), miR-765 eliminated lipids in clear cell renal cell carcinoma and acted as a tumor suppressor." (PMID 33686960, 2021).
Insulin resistance (1 paper, 2016). Increased resistance towards insulin, that is, diminished effectiveness of insulin in reducing blood glucose levels. "Concerning mRNAs, Slc1a5 was associated with hepatic glutamine uptake; Plp2 was able to increase ER-stress induced neuronal apoptosis while Cpeb1 was related with angiogenesis in chronic liver disease and involved in induction of insulin resistance." (PMID 27677588, 2016).
Mast Cell Tumor (1 paper, 2022). "Given the rarity of the identified variant, its predicted deleterious effect and the known function of proteolipid protein 2, a small transmembrane lipoprotein associated with skin cancer, we proposed a novel candidate gene associated with mast cell tumors." (PMID 36139188, 2022). "In summary, it is postulated that the congenital mast cell tumor displayed by the calf reported in this study might be associated with the identified X-chromosomal missense variant in PLP2." (PMID 36139188, 2022). "Here, we present a spontaneous large animal model for similar diseases in other mammal species and add PLP2 to the list of candidate genes for metastatic mast cell tumors." (PMID 36139188, 2022).
monoclonal gammopathy of undetermined significance (1 paper, 2020). "To assess the potential that PLP2 is crucial for myeloma, we examined PLP2 expression in the normal plasma cell (NPC), monoclonal gammopathy of undetermined significance (MGUS), smoldering multiple myeloma (SMM), and MM patients using GEO datasets." (PMID 32596309, 2020).
myeloma (1 paper, 2020). "In the present study, PLP2 was expressed significantly higher in aggressive subgroups (MS, MF, and PR), which were characterized by high-risk myeloma and related to an adverse prognosis." (PMID 32596309, 2020). "In this study, we analyzed the prognostic significance of PLP2 expression in MM patients using IHC analysis and GEO datasets and correlated with markers of myeloma activity, such as lower serum levels of ALB, higher serum levels of β2-MG, LDH, and CRP." (PMID 32596309, 2020).
myocardial hypertrophy (1 paper, 2018). "For example no report was found for the role of proteolipid protein 2 in myocardial hypertrophy, and very few reports investigating whether fibulin 2 contributes to cardiac remodeling." (PMID 29872491, 2018).
ovarian carcinoma (1 paper, 2024). A malignant neoplasm originating from the surface ovarian epithelium. "Moreover, miR-422a mediates the intercellular interaction and targets PLP2 to promote ovarian cancer (OC) development within exosomes." (PMID 38609925, 2024).
sarcoma (1 paper, 2012). A usually aggressive malignant neoplasm of the soft tissue or bone. "PLP2 enhances chemotaxis of human osteogenic sarcoma cells and PLP2 downregulation is associated with decreased metastasis in a mouse model of cancer." (PMID 22134506, 2012).
X-linked intellectual disability (1 paper, 2021). An X-linked intellectual deficiency in which not enough information is known, reported or published to indicate whether a gene causes non-syndromic or syndromic presentations. "Among these genes, PLP2, CCDC22, and SYP mutations were associated with X-linked intellectual disability." (PMID 34659328, 2021).